UCP3 (uncoupling protein 3)
Diseases named in the same sentence as UCP3 in open-access papers (continued):
Sharing a sentence is not in itself a finding about the gene and the disease.
Obesity (continued). "This review provides an overview of the role played by UCP1 and UCP3 in mitochondrial uncoupling/functionality as well as EM and suggests that they are a potential therapeutic target for treating obesity and its related diseases such as type II diabetes mellitus." (PMID 25713540, 2015). "The activation of RXR/PPARδ in muscle by CNX-013-B2 and increased mRNA expression of UCP3 could be one of the reasons for the protection from high fat-induced insulin resistance and obesity." (PMID 25143786, 2014). "Mutations in the gene encoding UCP3 have been discovered in some individuals suffering from severe obesity and non-insulin-dependent diabetes mellitus." (PMID 23092275, 2013). "Some of the obesity-associated genes in this study have known functions, ADIPOQ is known to decrease body weight by increasing lipid oxidation in muscles and other organs, and UCP3 plays an important role in human energy homeostasis." (PMID 23950976, 2013). "And our results did not support the association between UCP2 Ala55Val, UCP3 -55C/T polymorphisms and obesity in the populations investigated." (PMID 23560041, 2013). "Thus, caution is appropriate in ascribing a whole body thermogenic function and protection against obesity to UCP2 or UCP3." (PMID 16968550, 2006). "In conclusion, the present study enrolling a cohort of admixed Brazilian children could not detected causality between the six UCP3 SNP and obesity." (PMID 36810017, 2023). "Besides SIM1 and MC4R, the haploinsufficiency of proprotein convertase 1 (PCSK1), melanocortin 2 receptor accessory protein 2 (MRAP2) in the brain, iroquois homeobox 3 (IRX3) in fat or uncoupling protein 3 (UCP3) in mitochondria are also responsible for human obesity." (PMID 31124015, 2019). "Therefore, the upregulation of UCP3 in females may prevent the occurrence of obesity-induced secondary disorders such as cardiovascular diseases and diabetes." (PMID 31806023, 2019). "Thus, our observation of increased Ucp-3 expression in eWAT of Ogg1Tg mice is consistent with their increased proton leak and higher expression of fat oxidation genes, as well as with their resistance to diet-induced obesity." (PMID 30291284, 2018). "Furthermore UCP3 has a target site for miR-17a which is also down regulated in human obesity." (PMID 27902747, 2016). "Therefore, we speculate that UCP3 facilitates mitochondrial fatty acid oxidation and decreases oxidative stress, thus slowing the progression of obesity." (PMID 27473111, 2016). "Therefore, the UCP3 gene could be an interesting target, not only for lipid metabolism, but also for the treatment and prevention of obesity and metabolic-related diseases in dogs." (PMID 25495519, 2014). "However, they were not able to find any association of the UCP2 Ala55Val and UCP3-55C/T polymorphisms with obesity, which is in conflict with our data." (PMID 24804925, 2014). "Numerous studies have investigated the possibility that the amount of energy lost as a result of uncoupling between ATP generation and mechanical work may be reduced in obesity prone subjects, particularly in muscles which express UCP3 and where uncoupling appears larger than in other tissues." (PMID 23935869, 2013). "However, the UCP2 Ala55Val and the UCP3 −55C/T polymorphisms are not candidate loci for susceptibility to obesity in any ethnic population." (PMID 23560041, 2013). "Thus, the pharmacological stimulation of UCP3 activity could result in beneficial effects against obesity and type 2 diabetes mellitus." (PMID 23092275, 2013). "However, UCP2 may protect against atherosclerosis through reduction of oxidative stress and both UCP2 and UCP3 may protect against obesity." (PMID 16968550, 2006). "The 7CafD females developed a less favourable obesity phenotype than 7CafD males: they accumulated more WAT, and exerted a reduced expression of FAO genes (Cpt1β and Ucp3) in muscle and of the thermogenic gene (Dio2) in WAT." (PMID 39596499, 2024).
Obesity (continued). "A strong 36–49% decrease in cardiac UCP3 content was also observed in the MC4RKO rat, a rodent model with marked obesity, insulin resistance, and hyperinsulinemia." (PMID 30374710, 2018). "RSE sharply increased the mRNA levels of PPARs and target gene UCP3, thereby suggesting that RS prevents HF-diet-induced obesity in C57BL/6 mice mainly through the activation of PPARs and UCP3 signaling." (PMID 28507819, 2017). "In the present study, we performed genetic associations using a large-scale cohort to assess the impact of the UCP3 and RPTOR SNPs on obesity-related traits in modern humans." (PMID 25533680, 2014). "Although the physiological roles of UCP2 and UCP3 are less well established, most studies suggested that UCP2 and UCP3 gene clusters could play important roles in energy metabolisms and body mass regulation, and polymorphisms in these two genes might contribute to obesity." (PMID 23560041, 2013). "Mice with muscle-specific overexpression of Ucp3 did not develop obesity and showed increased energy metabolism and normal glucose tolerance upon high-fat feeding." (PMID 31312229, 2019). "Because of the conflicting reports on the effect of non-insulin-dependent diabetes on UCP3 expression in the heart, we first set out to quantify cardiac UCP3 levels in a panel of rodent models of obesity, insulin resistance and type 2 diabetes." (PMID 30374710, 2018). "In heart from rodent and human with obesity, UCP2 and UCP3 may protect cardiomyocytes from death and from a state progressing to heart failure by downregulating programmed cell death." (PMID 27642497, 2016). "UCP3-55C/T and the RPTOR-26934C/T may only have subtle effects on the development of obesity-related traits in the present humans." (PMID 25533680, 2014). "Energy wastage and protection from obesity were initially suggested to be significant functions of UCP2 and UCP3 due to their homology to UCP1 and their distribution in tissues, such as white adipose tissue and muscle, that could dissipate energy." (PMID 16968550, 2006). "However, while UCP3 is expressed in BAT, no role in non-shivering thermogenesis is apparent, as none of the expected phenotypes of cold sensitivity or obesity are observed in Ucp3-/- mice." (PMID 33211703, 2020). "An even stronger decrease in cardiac UCP3 content was observed in the LoxTB MC4R−/− mice (28–34% decrease) and LepR/Nestin-cre mice (38–40% decrease), two other models of type 2 diabetes which are also characterized by severe obesity, insulin resistance, hyperinsulinemia, and glucose intolerance." (PMID 30374710, 2018). "Importantly, Tfe3 KO mice showed down‐regulation of genes involved in thermogenesis, including Ucp1 and Ucp3, and oxidative genes such as Pparα in the BAT, which account, at least partially, for their reduced energy expenditure and diet‐induced obesity." (PMID 28283651, 2017). "However, the data suggesting an effect of UCPs on obesity remains uncertain, with two recent papers reporting no linkage or association with UCP2 or UCP3 alleles, while another reports association of UCP3 alleles with measures of body composition in women." (PMID 16968550, 2006). "On the other hand, several studies reported an important role of UCP3 in FAO and oxidative damage prevention by mitochondrial ROS, stating that UCP3 may facilitate FAO by transporting FAs into the mitochondria, thus proposing a protective role for this protein in obesity." (PMID 35807797, 2022). "Overall, our genetic association analyses including seasonality on a large-scale cohort showed that the UCP3-55C/T and the RPTOR-26934C/T did not influence obesity-related traits." (PMID 25533680, 2014). "At adulthood, neither maternal obesity nor litter size reduction affected markers involved in fatty acid and energy metabolism (CPT-1, ATGL, or UCP3)." (PMID 19606226, 2009).
Obesity (continued). "Thus, the induction of diabetes and obesity by the HFD seems related mainly to UCP1 and UCP2 expression in adipose tissue, but not to the expression of UCP2 and UCP3 in skeletal muscle." (PMID 35323702, 2022). "Ucp1, Ucp2, and Ucp3 expressed in BAT could generate heat after being activated by fatty acids and could play roles in nonshivering thermogenesis, diabetes, and obesity." (PMID 28665305, 2017).
diabetes (34 papers, 2006 to 2025). "Reduced UCP3 in prediabetes and diabetes is associated with insulin resistance, but the function of UCP3 is unclear." (PMID 40308937, 2025). "UCP2 has been said to act as adiposity angel and diabetes devil, whereas increased expression of UCP3 has been suggested to be associated with weight loss success." (PMID 19769793, 2009). "The UCP2/UCP3 locus is on chromosome 11 and has been linked with diabetes-related phenotypes in human and animal models." (PMID 17150099, 2006). "Although three SNPs of UCP1 were associated with DR in participants of poor glucose control, and one SNP of UCP3 was found to be associated with DR in diabetes patients with well controlled hyperglycemia, the significance did not remain after Bonferroni correction was applied." (PMID 32028915, 2020). "Several gene polymorphisms of UCP1, UCP2, and UCP3 were reported to be associated with diabetes." (PMID 23841103, 2013). "Furthermore, Hmgcs2, Ucp3, and Pck1 are increased and expressed in Akita mice hearts, and these highly interacting DEGs correlate with their cardiac expression and the importance of their functions in numerous signalling pathways associated with cardiomyopathy in diabetes." (PMID 41007634, 2025). "Diabetes and insulin resistance were described as conditions under which the expression of UCP3 is altered." (PMID 37047436, 2023). "Among the top upregulated genes in response to HFD/STZ-induced diabetes within each cell population were transcripts for Pdk4, Angptl4, Txnip, Postn, Hmgcs2, and Ucp3, of which several have been previously involved in heart failure." (PMID 37010266, 2023). "Similar to diabetes, high-fat diets or maternal over-nutrition increased the cardiac expression of UCP3." (PMID 37047436, 2023). "UCP3 is expressed in skeletal muscle, and upregulation of UCP3 has been reported in various conditions characterized by skeletal muscle atrophy, including denervation, diabetes, cancer, and sepsis." (PMID 36499637, 2022). "In regard to diabetes mellitus, overexpression of UCP3 improves glucose tolerance and protected the animals against fat-induced insulin resistance." (PMID 34829617, 2021). "The functional benefit of uncoupling protein induction in diabetes is also supported by the finding that overexpression of UCP3 (that functions similarly to UCP2 but shows distinct expression profile) is protective against glucose-induced damage in neurons." (PMID 27128320, 2016). "Supporting the role of UCP3 in diabetes, drugs for diabetes treatment can restore the expression of UCP3 mRNA in skeletal muscle of patients with T2DM and impaired glucose tolerance." (PMID 26713091, 2015). "In a Finnish diabetes prevention study, three variants in the UCP2 gene, one variant in the UCP2-UCP3 intergenic region, and five variants in the UCP3 gene were explored." (PMID 23841103, 2013). "In this study, mRNA expression of mitochondrial UCP3 was significantly elevated with diabetes, suggesting that this may be a compensation mechanism in response to the diabetes-induced changes in substrate utilisation." (PMID 34539423, 2021). "UCP3 is implicated in fatty acid (FA) metabolism, and patients with diabetes have low rather than high UCP3 protein content." (PMID 29529994, 2018). "In several pathophysiological conditions such as insulin resistance, diabetes, and postischemia stressed heart, chronic exposure to elevated circulating FFAs leads to increased UCP3 as adaptations that afford protection against the detrimental effect of an acute FFA load." (PMID 27642497, 2016). "The progress in the role of UCP1, UCP2, and UCP3 on diabetes mellitus is summarized in this review." (PMID 23841103, 2013). "Some interactions with a nominal p≤0.01 were found between sex and SNPs in the UCP1 and UCP3 gene; between smoking, diabetes, hypertension and SNPs in UCP5 and SIRT5; and between SNPs in the UCP5 gene and the UCP1, SIRT1, SIRT3, SIRT5, and SIRT6 genes in association with plaque phenotypes." (PMID 22087257, 2011).
diabetes (continued). "The association between the UCPs genes and diabetes has been investigated by many studies, and the most often studied SNPs are the rs1800592 (−3826A/G) of the UCP1 gene, the rs659366 (−866G/A), rs660339 (Ala55Val), and Ins/Del of the UCP2 gene, and the rs1800849 (−55C/T) of the UCP3 gene." (PMID 32028915, 2020). "This goes in accordance with similar findings in the literature where upregulated UCP3 and LDH levels have been reported during states of insulin insufficiency, diabetes, and fasting." (PMID 39377070, 2024). "Diabetes increases the cardiac expression of UCP2 and UCP3 mRNA." (PMID 37047436, 2023). "UCP3, MCAD and PDK4 are peroxisome proliferator-activated receptor α (PPARα) targets, a transcription factor that is activated by fatty acid ligands to upregulate fat metabolism, and is increased in diabetes." (PMID 24063408, 2013). "Furthermore, the majority of studies support the view that high UCP3 expression is protective, although this may not be the case in the presence of co-morbidities such as diabetes." (PMID 37047436, 2023).
Insulin resistance (30 papers, 2008 to 2025). Increased resistance towards insulin, that is, diminished effectiveness of insulin in reducing blood glucose levels. "Previous studies have shown mild uncoupling is an antioxidant factor, that loss of UCP3 is associated with insulin resistance, and that the restoration of UCP3 protein content improves insulin sensitivity." (PMID 32760285, 2020). "Using oral glucose tolerance test it was further shown that insulin resistance correlated with the decrease in UCP-3 caused by simvastatin." (PMID 26345110, 2015). "The second model describes the regulation of two nuclear encoded mitochondrial genes that have been associated with insulin resistance, UCP3 and PDK4." (PMID 19787081, 2008). "However, insulin resistance and type 2 diabetes are associated with only a partial deficiency in UCP3, and it remained unknown if a partial deficiency was sufficient to make the heart more vulnerable to MI and I/R injury." (PMID 30374710, 2018). "Serpine 1, an adipokine in thrombosis and insulin resistance regulation, was substantially upregulated, and genes involved in lipid metabolism, including Slc27a2, Acsm3, Acot1, and Ucp3, were dramatically decreased in BAT of BMRKO-HFD mice." (PMID 37734559, 2023). "Taken together, the study shows PPARδ enhances fatty acid utilization and uncoupled respiration via UCP3 and protects against EtOH-induced lipotoxicity and insulin resistance in skeletal muscle." (PMID 32760285, 2020). "Interestingly, high levels of myocardial SREBP1 have been reported in patients with pressure overloaded heart and metabolic syndrome and might be causally related to selective insulin resistance and inhibition of uncoupling protein 3 (UCP3) expression in the mouse heart." (PMID 32110930, 2020). "The mitochondrial uncoupling protein 3 (UCP3) is down-regulated in the heart with insulin resistance." (PMID 30374710, 2018). "We previously reported a decrease in cardiac UCP3 protein levels in experimental rat and mouse models of hyperinsulinemia and insulin resistance." (PMID 30374710, 2018). "After confirming that myocardial UCP3 levels were systematically decreased by 20–49% in animal models of insulin resistance and type 2 diabetes, we genetically engineered Sprague–Dawley rats with partial loss of UCP3 (ucp3+/−)." (PMID 30374710, 2018). "Our results also support that the role of UCP3 in skeletal muscle is to improve insulin resistance and increase energy expenditure." (PMID 30360437, 2018). "The results inversely correlated the levels of UCP3 in simvastatin treated patients with degree of insulin resistance." (PMID 26345110, 2015). "HP/HI induced insulin resistance and lipid storage was accompanied by increased Cd36, Acot1, and Ucp3 mRNA levels." (PMID 26649034, 2015). "In the present study we observed myocardial insulin resistance and altered mitochondrial ROS generation in association with decreased MCO, and UCP-3 expression in intrafibrillar myocardial mitochondria in older beagles." (PMID 25078106, 2014). "Further, a marked increase in uncoupling protein 3 (Ucp3) and Krüppel-like factor 15 (Klf15) expression in the skeletal muscle may promote lipid utilization and help mitigate lipid-induced insulin resistance in Ctrp10 KO female mice." (PMID 37961647, 2025). "Moreover, mice overexpressing UCP3 in skeletal muscle weigh less, have a decreased amount of adipose tissue, are protected from fat-induced insulin resistance, and have increased resting oxygen consumption." (PMID 38983274, 2024). "This fact may explain the downregulation of genes related to β-oxidation (CPT1A, CPT1B, and UCP3) in supplemented calves and may represent a protection mechanism against the development of diet-induced insulin resistance." (PMID 36837780, 2023). "In PAI-1-/- mice, increased skeletal muscle UCP-2 and UCP-3 may contribute to increased metabolic rates and energy expenditure, leading to protection against insulin resistance." (PMID 29163785, 2017).
Insulin resistance (continued). "Thus, cardiac UCP3 content is consistently decreased in obese, insulin-resistant, and type 2 diabetic animals, and a common denominator to this decrease is the development of hyperinsulinemia mediated by insulin resistance." (PMID 30374710, 2018). "We also demonstrated that hyperinsulinemia triggers insulin resistance in the heart, which in turn induces lipogenic transcription factor SREBP-1 and subsequent down-regulation of UCP3 expression." (PMID 30374710, 2018).